HIF1A (hypoxia inducible factor 1 subunit alpha)
Diseases named in the same sentence as HIF1A in open-access papers (continued):
Sharing a sentence is not in itself a finding about the gene and the disease.
tumor (continued). "In an attempt to identify metabolically hybrid tumor cells, others used mathematical modeling integrating gene expression with metabolic pathways based on AMPK and HIF1α gene signatures, two critical regulators of OXPHOS and glycolysis, respectively." (PMID 35193955, 2022). "Another mechanism for the suppression of angiogenesis involves a recently identified tumor angiogenesis inhibitor protein, connexin 43 (Cx43), which functions by downregulating VEGF via HIF-1α." (PMID 36297535, 2022). "OPN also exerts its function by activation of hypoxia-inducible factor-1 alpha (HIF-1α) pathways via the PI3k/AKT pathway, which leads to enhanced tumor cell survival, proliferation, invasion, EMT, and angiogenesis." (PMID 36499654, 2022). "Although various studies recognize HIF-1α and HIF-2α as promoters at the onset of various tumor entities, their role during tumorigenesis is positively associated with malignant progression." (PMID 35745875, 2022). "The combination of the HIF-1α inhibitor PX-478 and an anti-PD-L1 antibody increased dendritic cell (DC) and CD8 + T cell activation and dramatically suppressed tumor growth in a glioma mouse model." (PMID 35907881, 2022). "Metformin was shown to upregulate AMPK signaling and thus downregulate HIF-1α, transforming growth factor-β (TGF-β) and interleukin 8 (IL-8) in co-culture of CAFs with human breast cancer lines and thus preventing tumor-stroma crosstalk." (PMID 36582801, 2022). "ACF is a specific inhibitor of hypoxia-inducible factor (HIF-1α), which prevents the formation of HIF-1α/HIF-1β dimer, inhibiting the expression of vascular endothelial growth factor and consequently, tumor growth." (PMID 34358097, 2021). "In the hypoxic glioblastoma TME setting, there is an increased expression of HIF1a in tumor tissue leading to increased expression of CD39 and CD73 on tumor cells, immune cells, stromal cells, and endothelial cell, leading to increased extracellular adenosine." (PMID 34222022, 2021). "Matrix metalloproteinase 13 (MMP-13) in NPC-related exosomes upregulates vimentin and reduces cadherin to facilitate tumor invasion, metastasis and angiogenesis; on the other hand, MMP13 expression is trans-activated by hypoxia-inducible factor α (HIF1α) 6,52." (PMID 34239345, 2021). "VEGF is a major regulator of angiogenesis and is mainly produced by macrophages, tumor cells, and fibroblasts; VEGF expression is mediated by HIF-1α." (PMID 34248676, 2021). "CAF can produce tumor-promoting cytokines such as CXCL12, IL-6, HIF1a, and TGF-b2, and monocytic MDSCs can promote tumor epithelial to mesenchymal transition (EMT)." (PMID 34831357, 2021). "Mechanistically, both miRNA-34a and miR-200c directly target HIF1-α and subsequently downregulate VEGFR, MMP9 and CXCR4, although combined miRNA-34a and miR-200c delivery suppresses mouse xenograft tumor development as effectively as individual delivery." (PMID 33673143, 2021). "Hypoxia inducible factor-1α is a key gene for mammalian cells to adapt to hypoxia and tumor cell glycolysis dependence, and IDH2 has been found to promote Warburg effect through HIF-1α." (PMID 34513821, 2021). "The transcription factor hypoxia inducible factor-1alpha (HIF-1α) mediates adaptive responses to oxidant stress, promotes inflammatory gene expression, and contributes to tumor proliferation." (PMID 35002707, 2021). "By blocking HIF-1α/VEGF pathway, sorafenib reduces microvessel density and inhibited tumor vascularization." (PMID 33933107, 2021). "In mice with HIF1α-deficient NK cells, tumor control was enhanced either directly by increased IL-18 signaling that improved NK cell effector responses or indirectly through an absence of tumor-infiltrating NK cells, which altered the VEGF/VEGFR axis affecting productive angiogenesis." (PMID 34396954, 2021). "HIF-1α and GLUT1 are considered intrinsic hypoxia markers and have been studied the most in various tumours." (PMID 34281558, 2021).
tumor (continued). "Tumor cells are well adapted to a hypoxic environment, and VDAC1 is regulated by oxygen tension in HIF-1α-dependent manner at the levels of transcription and protein modification." (PMID 34381722, 2021). "A significant correlation was observed between high HIF1α and low HACE1 expression in both tumor cohorts, highlighting the inverse relationship between HACE1 and HIF1α levels in vivo." (PMID 33603169, 2021). "Therefore, silencing ID1 may restore or increase tumor sensitivity to HIF1α inhibition." (PMID 34820369, 2021). "In particular, PD‐L1 and PD‐L2 exhibited a close relationship with upregulation of tumor glucose metabolism (GLUT1) and hypoxia (HIF‐1α), which play essential roles in the mechanism of 18F‐FDG uptake within tumor cells." (PMID 34363337, 2021). "Hypoxia-inducible factor-1 alpha (HIF-1α), for instance, is a key transcriptional regulator in adaptive response to hypoxic tumor microenvironment, which represents an interesting cancer drug target." (PMID 35048009, 2021). "Significant changes in tumour angiogenesis, cancer cell proliferation, apoptosis, HIF1α levels, HIF-1 target genes and ABCG2 were found both in vitro and in tumour tissue." (PMID 34546500, 2021). "In response to hypoxic conditions, high expressions of HIF-1α and HIF-2α have been correlated with poor prognosis of patient outcome in various tumor forms." (PMID 33805447, 2021). "Therefore, we could clarify the clinical roles of IGFBP3, HIF-1α and HIF-2α in EOC progression: HIF-1α being important in early hypoxia response and HIF-2α playing in prolonged hypoxia that could be associated with the overcome of tumor growth restriction." (PMID 34824343, 2021). "HIF-1α and HIF-2α were previously thought to promote tumor progression through largely overlapping functions." (PMID 34931765, 2021). "As part of HIF-1α/CASC15/SOX4/β-catenin axis, CASC15 plays an essential role in cell proliferation, invasion, and tumor development in NSCLC." (PMID 34745939, 2021). "LncRNA H19, HOTAIR, and MVIH mainly regulate the proliferation, migration, invasion and angiogenesis of tumor cells by regulating VEGF, VASH2, and miR138/HIF1α axis." (PMID 34616746, 2021). "Iodine deprivation causes reactive oxygen species (ROS) production, stabilization of HIF-1α and VEGF release through the activation of signals in the tumor thyrocytes that induce microvascular expansion to facilitate enhanced delivery of iodide." (PMID 34204889, 2021). "In summary, these studies indicate compensatory effects of HIF-1α and HIF-2α on tumor angiogenesis, with HIF-1α contributing to vessel growth while HIF-2α responsible for vessel maturation." (PMID 34202979, 2021). "Overall, our study confirmed that 1) HECTD2 is up-regulated in RCC and aggravates RCC progression; 2) miR-320a functions as a tumor suppressor in RCC by targeting HECTD2; 3) HIF-1α induces HECTD2 upregulation by repressing miR-320a." (PMID 35004677, 2021). "In the present study, we demonstrated that by mediating Akt ubiquitination and activation, regulating HIF-1α transcriptional activities, and hexokinase-2 expression, TRAF6 played an important role in the regulation of tumor glycolysis." (PMID 34409101, 2021). "In the previous publication, it is shown that sub-curative radiation increases tumor cell proliferation, migration, and invasion in a rat model of primary human GBM primarily by the increased expression level of MMP2, HIF-1α, and SDF-1α." (PMID 33544755, 2021). "In another study, tumor cell-derived succinate resulted in TAM polarization toward a pro-tumor phenotype through a succinate receptor (SUCNR1) and was dependent on the PI3K/HIF1α signaling pathway that resulted in enhanced metastasis." (PMID 33968034, 2021). "Hypoxia frequently mediates chemoresistance and tumor aggressiveness via the induction of HIF-1α in the tumor microenvironment, and targeting HIF-1α is a potential strategy to increase the effect of tumor chemotherapy." (PMID 34948250, 2021).
tumor (continued). "Reassuringly, the combination treatment with AZ produced a more significant reduction in tumor growth and angiogenesis, although the influence of the combined treatment on VEGF and HIF1α pathways remained uninvestigated." (PMID 34948200, 2021). "Silencing HIF-1α was found to significantly suppress the production of CSF2 and lactate in KRAS mutant tumor cells, abrogating the ability to induce TAM-like changes in macrophages." (PMID 33833221, 2021). "Especially, the nuclear p300 complex that includes pERK1/2 and integrin αv monomer was shown to regulate TH target genes critical for tumor cell biology, such as COX-2, hypoxia inducible factor 1 alpha (HIF-1α), and ERα." (PMID 35008863, 2021). "Coinciding with lncRNA KB-1980E6.3, higher levels of HIF-1α, c-Myc, and CD44 were detected in most tumor tissues, and their levels were increased in accompany with tumor stages." (PMID 33469161, 2021). "In the Hif1α signaling pathway, TME-derived growth factors IGF and EGF are likely promoting HCC-tumor derived ARNT, which is in turn promoting the expression of known pro-angiogenesis genes PAI1, and TGFA." (PMID 33995488, 2021). "The enzymatic activity of PHD was also increased in the tumor lysate, demonstrating an important role for PHD in the proteasomal degradation of HIF-1α." (PMID 33806179, 2021). "HIF-1α enabled the dual roles of TGF-β in regulating glucose metabolism and the cell cycle of tumor cells under normoxia and hypoxia." (PMID 34930376, 2021). "Metformin blocks HIF1α-phosphofructokinase (PFK), which catalyzes the third step of glycolysis, and lactate release in hepatoma cells and tumor tissues, thereby attenuating HCC growth." (PMID 33920670, 2021). "LOX/LOXL expression remodels ECM at metastatic sites to facilitate recruitment of bone marrow-derived cells, an effect dependent on HIF-1α and HIF-2α activity in tumor cells." (PMID 34202979, 2021). "Many studies with the knocking down of HIF-1α and HIF-2α in cancer cells have proven the significant role of these factors in promoting malignant growth and tumor resistance to hypoxia, as well as chemo- and radiotherapy." (PMID 33806538, 2021). "For proneural GSCs, pharmacologic blockade of HIF-1α activity by GN44028 and of Smad3 activity by the Smad3 inhibitor, (E)-SIS3 or a palmitoylation inhibitor, 2-BP, effectively suppressed tumor growth and extended survival rates in animals with xenografts." (PMID 34707087, 2021). "The expression of glucose transporter 1 (GLUT1) for glucose metabolism and HIF-1α in response to hypoxia play a crucial role in the accumulation of 18F-FDG, and correlate with tumor progression and spread." (PMID 33441183, 2021). "While many HDAC4 targets have been identified, we focused on HIF1α, one of the central players of tumor progression and drug response and VEGFA, one of the best-characterized HIF1α targets." (PMID 34359722, 2021). "Conversely, overexpression of CHCHD4 in tumour cells was shown to increase basal cellular OCR and intracellular hypoxia, and led to enhanced HIF-1α stabilisation in hypoxia, all of which were blocked by the CIV inhibitor sodium azide." (PMID 33599699, 2021). "Treatment of ZnPP, a HO-1 inhibitor, suppressed HIF-1α expression and VEGF production, accompanied by the enhanced proliferation of HCT-15 cells, suggesting that the angiogenesis for tumor growth is mediated by HIF-1α and VEGF." (PMID 34572050, 2021). "In tumor-bearing mice, MDSCs infiltrated in TME express high levels of PD-L1 that is induced by HIF-1α." (PMID 34359674, 2021). "Under hypoxic conditions, EGR1 increases VEGFA expression, mediated by HIF1α, and directly activates VEGFA transcription, thus promoting the formation of blood and lymphatic vessels in the tumor." (PMID 33842351, 2021). "For example, linc-p2122 and HISLA23 stabilize HIF-1α protein by blocking its interaction with VHL and PHD2 respectively, and thus enhance glycolysis in tumor cells." (PMID 33637716, 2021).
tumor (continued). "In this study, we investigated the role of HIF-1α and its regulatory pathways in the interactions between CLL cells and their protective tumor microenvironment." (PMID 34207596, 2021). "Hypoxia inducible factor 1-alpha (HIF1α), the master regulator of hypoxia, further drives upregulation of VEGF which has been shown to enhance tumor survivability through activation of the MAPK/ERK pathway." (PMID 34987525, 2021). "HIF-1α, released in the TME from tumor cells, is another protein that has a crucial role in MDSC differentiation toward TAMs." (PMID 34025641, 2021). "We further demonstrated that knockdown of CTNND1 not only enhanced intrinsic metastatic functions including migration and invasion, but also facilitated tumor recruitment to bones, an event through the CXCR4/CXCL12 axis by activating PI3K/AKT/HIF-1α pathway." (PMID 34830862, 2021). "To investigate the peptide and receptor expression in the hypoxic area of the tumor, we analyzed the co-localization of PACAP or PAC1R with HIF-1α on human GMB sections by double-immunofluorescence analysis." (PMID 34440169, 2021). "Results demonstrated a significant reduction in tumor size and the highest levels of IFN-γ and IL-17 and the lowest levels of IL-4 FoxP3, HIF-1α, VEGF, MMP-2, and MMP-9 in the IT+IP+TEX-treated group." (PMID 34194604, 2021). "Previous studies have shown that hypoxia induces HIF-1α and HIF-2α, which stimulate the formation of tumor vasculatures, including angiogenesis and VM formation, through vascular endothelial growth factors." (PMID 34287575, 2021). "Because VEGF is a downstream gene of HIF-1α, VEGF expression is decreased when the expression or function of HIF-1α is inhibited, and HIF-1α can regulate the expression of other genes that promote tumour progression." (PMID 35004308, 2021). "Hypoxic conditions in the tumor trigger HIF-1α activation and, in turn, an upregulation of the CD73-adenosine pathway, which is able to promote tumor growth and metastasis." (PMID 34539333, 2021). "In certain studies, the staining level and pattern were described in correlation with hypoxia, HIF1α expression, and FDG-PET-CT images in various tumor types." (PMID 35029792, 2021). "qRT‐PCR and Western blot assays were used to examine the expression levels of Piezo1, HIF‐1α, VEGF, vimentin and E‐cadherin in peritoneal metastatic GC tumour tissues." (PMID 33439514, 2021). "Deletion of HIF-1α or one of it targets, VEGF-A specifically in CD8+ T cells limits T cells migration and infiltration into tumor sites in LLC and B16-F10 subcutaneous models." (PMID 34202979, 2021). "Together, these data provide additional mechanistic insights into the tumor suppressor activity of HACE1, namely through the regulation of HIF1α." (PMID 33603169, 2021). "Macrophages are closely linked and aggregated by activating key transcription factors in tumor cells, such as NF-κB, STAT3, and HIF-1α." (PMID 34079469, 2021). "previous studies show that the inhibition of HIF-1α and COX-2 can effectively decrease tumor angiogenesis and growth." (PMID 34059044, 2021). "It is well known that HIF-1α has an essential role in cancer cell proliferation and invasion whilst MMP9 is crucial in tumour migration and progression." (PMID 33673181, 2021). "Immunohistochemistry analysis was conducted to detect the expressions of HIF-1α and VEGF-A in tumor tissues." (PMID 33830713, 2021). "In the same vein, HIF-1α overexpression was observed to slow down the growth of renal carcinoma in xenografts, whilst an increased HIF-2α expression favored the tumor growth." (PMID 34944758, 2021). "The alkaloid Berberine also downregulated HIF-1-α and its downstream target vascular endothelial growth factor (VEGF) and reduced tumor invasiveness resulting in an improved radiotherapy response." (PMID 34041023, 2021).
tumor (continued). "Current studies have confirmed that the activation of the MAPK and PI3K signaling pathways promotes the expression of HIF-1α, induces the production of downstream VEGF, promotes tumor angiogenesis, and indirectly promotes tumor growth." (PMID 34335854, 2021). "One other way is by increasing the expression of HIF-1α, as STAT3 is an upstream transcription factor for HIF-1α, in cancer cells and myeloid cells in the TME, which is critical for immunosuppression and tumor immune evasion." (PMID 34692527, 2021). "Of note, FBP1 was reported to be a tumor suppressor constantly deleted in ccRCC that inhibited glycolysis and PPP with direct inhibition of HIF-1α activity, putting FBP1 in the opposite position to PFKFB4." (PMID 34593007, 2021). "Transplanted tumor tissue samples were taken for hematoxylin and eosin (HE) staining, and the expression of VEGF, HSP90, HIF-1α, and MMP9 was evaluated via reverse transcription-quantitative PCR or immunohistochemistry." (PMID 34825004, 2021). "Hypoxia-inducible factor-1α (HIF-1α), as the main transcription factor during hypoxia, is significantly upregulated in the MES subtype and plays an important role in tumor angiogenesis and proliferation." (PMID 33875619, 2021). "Hypoxia also promotes the over-expression of HIF-1α protein and its downstream VEGF protein in tumor cells." (PMID 34093799, 2021). "Our results suggested Huaier revealed anti‐tumour effects in both in vivo and in vitro possibly through PI3K/AKT/HIF‐1α pathway." (PMID 33377619, 2021). "Then, we found that stable transfection of HIF-1α-shRNA into OSRC-2 cells led to markedly decreased growth and tumor weight of xenograft tumors compared with the NC-shRNA group." (PMID 34926261, 2021). "DCA reverses the Warburg effect in tumor cells by inhibiting PDKs, restoring PDH activity, boosting OXPHOS, and decreasing pyruvate and lactate levels, leading to decreased expression of HIF-1α." (PMID 34298883, 2021). "Another similar study demonstrated the tumor suppressor property of SIRT3 through its ability to suppress ROS and regulation of HIF-1α." (PMID 34803727, 2021). "At the end of the experiment, we performed CD31, HIF-1α, TUNEL, and Ki-67 assays to assess MVD, hypoxic degree, tumor cell apoptosis, and tumor cell proliferation, respectively." (PMID 33996599, 2021). "For example, the expression of HIF1α and HIF2α are mutually suppressed, and while HIF1α retards RCC tumor growth, HIF2α enhances RCC tumor growth." (PMID 34384473, 2021). "At the tumor level, the authors show that perturbation of TNC-mediated ECM stiffening or at a point in the regulatory pathway with HIF1α or one of its regulators miR-203 improved survival is observed in murine xenograft models of GBM." (PMID 35127517, 2021). "In summary, our study revealed that upregulation of the HIF-1α/miR-210 pathway can enhance the migration and invasion of CAFs, and CAFs from the primary foci of CRC can metastasize to distant organs and promote tumor metastasis." (PMID 34631221, 2021). "The results suggested that both HIF-1α and HECTD2 were up-regulated in RCC (compared with adjacent non-tumor tissues), and they had positive relationship." (PMID 35004677, 2021). "Abnormal expression of HDAC1 leads to overexpression of HIF-1α and VEGF in tumours, which subsequently promotes angiogenesis." (PMID 34395273, 2021). "Considering that tumor vascular normalization alleviates hypoxia in the TME, we investigated the expression of HIF-1α." (PMID 33976735, 2021). "As a very important member of the STAT family, STAT3 has been shown to be involved in cancer cell proliferation, metastasis, and angiogenesis in multiple reports, and STAT3 regulates tumour angiogenesis by regulating VEGF and HIF-1α." (PMID 33865381, 2021). "SiRNA-mediated knockdown of PKM2 resulted in an upregulation of tumor suppressors, including Bad, caspase 7, and E-cadherin, whereas oncogenes, such as MMP-2, MMP-9, HIF1α, and VEGF, were downregulated in the SK-OV-3 cells." (PMID 34131394, 2021).